RDH8 (retinol dehydrogenase 8)
Description:
Retinol dehydrogenase with a clear preference for NADP. Converts all-trans-retinal to all-trans-retinol. May play a role in the regeneration of visual pigment at high light intensity (By similarity).
Synonyms: PRRDH; SDR28C2; STGD5
Tractability: Antibody: its Gene Ontology location is reachable by antibodies, with high confidence; UniProt predicts a signal peptide or a membrane-spanning region.
Gene: Protein-coding gene on chromosome 19 (10,013,249 to 10,022,279, forward strand). Ensembl gene ENSG00000080511.
Subcellular location: Membrane
Subcellular location (Human Protein Atlas): Nucleoplasm; Cytosol; Midbody ring
Pathways (Reactome):
Sensory Perception: The canonical retinoid cycle in rods (twilight vision)
Gene Ontology:
Molecular function: all-trans-retinol dehydrogenase (NAD+) activity; all-trans-retinol dehydrogenase (NADP+) activity; estradiol 17-beta-dehydrogenase [NAD(P)+] activity
Biological process: retinol metabolic process; steroid biosynthetic process; visual perception; estrogen biosynthetic process
Cellular component: cytosol; plasma membrane; cytoplasm; membrane
Genetic constraint (gnomAD): Loss-of-function variants: 17 observed, 23.85 expected, observed/expected ratio (o/e) 0.71, 90% interval 0.49 to 1.07. The upper end of that interval is the gene's LOEUF score, 1.07, which puts it in group 4 of 6, group 1 being the genes least tolerant of losing a copy. Missense variants: 389 observed, 420.51 expected, observed/expected ratio (o/e) 0.93, 90% interval 0.85 to 1.01. Synonymous variants: 175 observed, 177.97 expected, observed/expected ratio (o/e) 0.98, 90% interval 0.87 to 1.12.
Homologues: Orthologues: chimpanzee RDH8 (99% identical), macaque RDH8 (97% identical), pig RDH8 (87% identical), dog RDH8 (85% identical), rabbit RDH8 (84% identical), rat Rdh8 (84% identical), mouse Rdh8 (83% identical), guinea pig RDH8 (81% identical), tropical clawed frog rdh8 (58% identical), zebrafish rdh8b (56% identical), zebrafish rdh8a (54% identical), tropical clawed frog XB1000829 (48% identical), and 13 more. Paralogues in human: DHRS7B (23% identical), DHRS7 (22% identical), DHRS7C (22% identical), DHRS2 (22% identical), DHRS4 (21% identical), HSD11B1 (21% identical), HSD11B1L (20% identical), DHRS11 (19% identical), DHRS4L2 (18% identical), CBR1 (16% identical), CBR3 (15% identical), HSDL2 (15% identical), and 1 more.
Diseases named in the same sentence as RDH8 in open-access papers:
RDH8 is named in the same sentence as 12 diseases in open-access papers, as found by Europe PMC text mining. Sharing a sentence is not in itself a finding about the gene and the disease. The quoted sentences say what the papers report.
retinal degeneration (18 papers, 2012 to 2025). Degeneration of the retina. "Together, our results indicate that JC3 and JC4 protect the retina of Abca4-/-Rdh8-/- mice from retinal degeneration caused by bright light injury." (PMID 39808594, 2025). "Functional declines of the retinas were observed in Abca4−/−/Rdh8−/− animals, along with retinal degeneration, which was linked to an aberrant buildup of bis-retinoids." (PMID 36227868, 2022). "To validate the therapeutic potential of JC3 and JC4 in vivo, we examined their effectiveness in 2 mouse models of retina degeneration Abca4-/-Rdh8-/- and RhoP23H/+knock-in mice." (PMID 39808594, 2025). "Collectively, these findings imply that Gsdme gene deficiency prevents retinal function decline and ameliorates light-induced photoreceptor ferroptosis and retinal degeneration in Abca4-/-Rdh8-/- mice by alleviating iron overload and lipid peroxidation." (PMID 41281747, 2025). "Similar to the efficacy observed with intraperitoneal injection, a single intravitreal injection of MitoTEMPO was also effective in alleviating light-induced retinal degeneration and photoreceptor ferroptosis in Abca4-/-Rdh8-/- mice." (PMID 41281747, 2025). "Concurrently with the genetic inactivation of the Rbp1 gene, pharmacological modulation of RBP1 activity with abnormal cannabidiol (abn-CBD) and other nonretinoid inhibitors provided substantial protection against retinal degeneration in Abca4−/−/Rdh8−/− mice." (PMID 40749832, 2025). "Triple knockout (Abca4−/−/Rdh8−/−/Rbp1−/−) mice were protected against light-induced retinal degeneration." (PMID 40749832, 2025). "We validated the therapeutic potential of these compounds in 2 mouse models of retina degeneration, Abca4-/-Rdh8-/- mice, a model of acute light damage, and in an RP model, P23H Rho knock-in mice." (PMID 39808594, 2025). "Cross-breeding these mice with the Rbp1−/− line resulted in Abca4−/−/Rdh8−/−/Rbp1−/− triple KO offspring that were largely protected against light-induced retinal degeneration." (PMID 40749832, 2025). "Knocking out GSDME significantly attenuated light-induced photoreceptor ferroptosis and retinal degeneration in Abca4-/-Rdh8-/- mice." (PMID 41281747, 2025). "To determine the optimal injection time point, we first characterized the retinal degeneration in this Abca4-/-Rdh8-/- mouse model over a period of three months." (PMID 37852949, 2023). "The neuroprotective effect of norbixin in Abca4-/- Rdh8-/- mice during the early curative supplementation confirms our previous observations in acute blue-light induced retinal degeneration model in vivo in the same mice." (PMID 32255762, 2020). "Abca4-/- Rdh8-/- mice are a model of STGD but also a broader model of retinal degeneration such as AMD." (PMID 32255762, 2020). "Mice with knockout of ATP-binding cassette subfamily A member 4 (Abca4) and retinol dehydrogenase 8 (Rdh8) genes are characterized by impaired clearing of atRAL and they were a model of light-induced retinal degeneration." (PMID 30626110, 2019). "By contrast, Abca4−∕−.Rdh8−∕− mice are described to have regional retinal degeneration and rosette formation as early as 6 weeks of age and advanced retinal degeneration by 3 months." (PMID 30038866, 2018). "Our animals had a similar rate of retinal degeneration than the albino Abca4−∕− mice and rosette formation was only found in one 12-month-old animal from a total of 25 Abca4−∕−.Rdh8−∕− animals examined light-microscopically up to an age of 25 months." (PMID 30038866, 2018). "In contrast to normal retinal morphology in Rdh8−/− mice, Rdh8−/−Abca4−/− mice display progressive retinal degeneration and Rdh8−/−Abca4−/− mice serve as a useful animal model to study Stargardt disease and AMD." (PMID 27879662, 2016). "Notably, treatment with the mitoROS scavenger MitoTEMPO mitigated ferroptosis in atRAL-loaded photoreceptor cells and dramatically relieved photoreceptor ferroptosis and retinal degeneration in light-exposed Abca4-/-Rdh8-/- mice." (PMID 41281747, 2025).
retinal degeneration (continued). "Combined deletion of retinal dehydrogenases, RDH12 and RDH8, results in mouse retinal degeneration." (PMID 33107823, 2020). "Interestingly, knockout of RDH8 (retinol dehydrogenase 8) which conducts all-transretinal aldehyde metabolism together with ABCA4 showed the retinal degeneration in mice." (PMID 25922843, 2015). "Indeed it has been shown that accumulation of all-trans-retinal in mice lacking the ABCA4 transporter (ATP-binding cassette transporter 4) and RDH8 (retinol dehydrogenase 8) are liable to retinal degeneration, particularly that induced by light." (PMID 23230433, 2012). "Moreover, BIO203 administered systemically protects visual functions and retinal structure in albino rats subjected to blue-light illumination and in the retinal degeneration model of Abca4−/− Rdh8−/− double knock-out mice following 6 months of oral complementation." (PMID 36982372, 2023). "Acute and chronic retinal degeneration following blue light damage (BLD) in BALB/c mice and aging of Abca4-/- Rdh8-/- mice, respectively, reproduce features of AMD and STGD." (PMID 32255762, 2020). "By contrast, this treatment induced no retinal degeneration and only a slight ERG loss in Abca4+/+ Rdh8+/+ Rpe65-Leu450 and rd8 background mice." (PMID 27992460, 2016). "Importantly, neither Abca4−/−/Rdh8−/− nor Abca4−/−/Rdh8−/−/Rbp1−/− mice revealed spontaneous retinal degeneration without specific exposure to intense bright light." (PMID 40749832, 2025). "By contrast, BIO203 did not limit retinal degeneration in ABCA4−/− RDH8−/− mice." (PMID 36982372, 2023). "Furthermore, as reported in another study, intraperitoneal (i.p.)injection of 11-cis-6-membered-ring-retinal to Abca4-/-Rdh8-/- mice that resemble many hallmarks of AMD and its juvenile form, Stargardt disease, prior to light illumination prevented the retinal degeneration in these mice." (PMID 31835521, 2019). "In order to see whether A2E is involved in the retinal degeneration induced by BLD we used Abca4+/+Rdh8+/+ mice, in which A2E does not accumulate in RPE cells as fast as in Abca4−/− Rdh8−/− mice." (PMID 27992460, 2016).
Stargardt disease (7 papers, 2016 to 2025). "It is thought to be primarily associated with the retina with a murine model of Stargardt macular dystrophy that contained double knockout Abca4−/− and Rdh8−/− exhibiting reduced inflammation." (PMID 36385764, 2022). "A third Stargardt disease mouse model is the pigmented Abca4−∕−.Rdh8−∕− mouse strain, generated by crossbreeding Abca4−∕− mice with Rdh8−∕− mice." (PMID 30038866, 2018). "Thus, we investigated the effect of the Rbp1 gene inactivation on the phenotype of the Abca4−/−/Rdh8−/− model of Stargardt disease." (PMID 40749832, 2025).
blinding (2 papers, 2013 to 2023). "For example, partial or complete loss of ABCA4 functions cause many blinding diseases in humans including retinitis pigmentosa, cone-rod dystrophy and Stargdardt macular dystrophy, but ABCA4 KO in mice does not cause blindness unless combined with a deletion of other genes such as RDH8." (PMID 24391722, 2013).
cone-rod dystrophy (2 papers, 2013 to 2022). Inherited retinal dystrophies that belong to the group of pigmentary retinopathies. "Retinol dehydrogenase 8 (RDH8) and ATP-binding cassette transporter 4 (ABCA4) deficient mice that develop cone-rod dystrophy (CORD) showed increased expression of TLR signalling elements." (PMID 38983565, 2022).
retinitis pigmentosa (2 papers, 2013 to 2015). Retinitis pigmentosa (RP) is an inherited retinal dystrophy leading to progressive loss of the photoreceptors and retinal pigment epithelium and resulting in blindness usually after several decades. "In the retina, deficiencies in Ccl3 reduce progressive photoreceptor death and monocyte recruitment in degenerative Abca4−/− Rdh8−/− mice, and in the Mertk−/− mouse model of retinitis pigmentosa." (PMID 25595590, 2015).
breast carcinoma (1 paper, 2021). "Furthermore, we generated an expression risk score for each of the breast cancer patients in the METABRIC Discovery, Validation and TCGA sets using the seven genes RDH5, RDH8, RDH10, RDH11, RDH12, RDH13, RDH14." (PMID 33436820, 2021). "To explore the expression patterns of the seven genes RDH5, RDH8, RDH10, RDH11, RDH12, RDH13, RDH14 in normal tissues as well as breast cancer tissue, we first drew a heat map of the expression levels of the genes across normal human tissues from GTEx portal." (PMID 33436820, 2021).
essential hypertension (1 paper, 2021). Hypertension that presents without an identifiable cause. "In summary, GRK4 and RDH8 are genetic risk factors for essential hypertension in Han Chinese in Xinjiang." (PMID 34297769, 2021). "Six non-synonymous mutations related to hypertension were identified, including GRK4 rs1644731 and RDH8 rs1801058, Mutations are predicted to affect 3D conformation, force field, transmembrane domain and RNA secondary structure of corresponding genes." (PMID 34297769, 2021). "Thus, GRK4 and RDH8 may serve as susceptibility genes for hypertension." (PMID 34297769, 2021). "In order to explore potential effects of GRK4 and RDH8 on hypertension pathogenesis, a PPI network was constructed." (PMID 34297769, 2021). "RDH8 is involved in vitamin A (retinol) metabolism and consequent biological processes related to hypertension." (PMID 34297769, 2021). "In a recent GWAS study, pathways and biological processes related to hypertension were discovered, including retinoids metabolism, related to RDH8 and NADP-retinol dehydrogenase and thus vitamin A metabolism." (PMID 34297769, 2021). "Low expression of LRAT, which may interact with RDH8, is an independent predictor of essential hypertension." (PMID 34297769, 2021). "Therefore, this study mainly studied how the two genes, RDH8 rs1644731 and GRK4 rs1801058, and their mutation sites play a role in the pathogenesis of hypertension in Han people in Xinjiang." (PMID 34297769, 2021). "GRK4 and RDH8 may interact with these proteins involved in hypertension." (PMID 34297769, 2021). "RDH8 may participate in two biological processes, vitamin A metabolism and hypertension." (PMID 34297769, 2021). "Another interaction protein of RDH8, BCO1 (Beta-carotene 15,15’-dioxygenase), was related to lycopene, and thus hypertension." (PMID 34297769, 2021). "Therefore, in this study, we focused on how RDH8 rs1644731 and GRK4 rs1801058 correlate with hypertension in Han people in Xinjiang." (PMID 34297769, 2021).
Retinal atrophy (1 paper, 2025). A nonspecific term denoting wasting, especially as a result of degeneration, of the retinal pigment epithelium (RPE) and neurosensory retinal cells. "Moreover, previous reports indicate that the photoreceptor-specific all-trans-retinol dehydrogenase 8 (Rdh8) is an assistant susceptibility gene for STGD1 and dry AMD, and its knockout accelerates retinal atrophy in Abca4 mutant mice." (PMID 39984833, 2025).
sarcoma (1 paper, 2021). A usually aggressive malignant neoplasm of the soft tissue or bone. "Interestingly, the G2 subgroup mainly contained the sarcomas with elevated expression of RDH11, RDH8, RDH16, CYP2A6, and ALDH1A2, all of them were strongly or slightly correlated with poor survival." (PMID 35186946, 2021).
cancer (2 papers, 2023 to 2024). A tumor composed of atypical neoplastic, often pleomorphic cells that invade other tissues. "In particular, there is limited information available regarding the involvement of SLC35E4, AKAP5, and RDH8 in malignancies; only a few bioinformatics studies have addressed their potential as prognostic predictors for cancer." (PMID 38561388, 2024).
RDH8 also shares sentences with these, for which no sentence is quoted: Hypertension (1 paper); Leber congenital amaurosis 13 (1).